ZNF134 (zinc finger protein 134)
Description:
May be involved in transcriptional regulation.
Synonyms: pHZ-15
Tractability: PROTAC: UniProt records ubiquitination sites on it; ubiquitination databases record sites on it.
Gene: Protein-coding gene on chromosome 19 (57,614,233 to 57,624,724, forward strand). Ensembl gene ENSG00000213762.
Subcellular location: Nucleus
Subcellular location (Human Protein Atlas): Nucleoplasm
Gene Ontology:
Molecular function: protein binding; DNA-binding transcription repressor activity, RNA polymerase II-specific; RNA polymerase II cis-regulatory region sequence-specific DNA binding
Biological process: negative regulation of transcription by RNA polymerase II; regulation of cytokine production; regulation of immune system process
Cellular component: nucleoplasm; nucleus
Genetic constraint (gnomAD): Loss-of-function variants: 5 observed, 2.32 expected, observed/expected ratio (o/e) 2.15. That is too few expected variants to judge how well the gene tolerates losing a copy. Missense variants: 540 observed, 542.47 expected, observed/expected ratio (o/e) 1, 90% interval 0.93 to 1.07. Synonymous variants: 176 observed, 184.93 expected, observed/expected ratio (o/e) 0.95, 90% interval 0.84 to 1.08.
Homologues: Orthologues: chimpanzee ZNF134 (99% identical), macaque ZNF134 (97% identical), tropical clawed frog zfx (21% identical), rat Zfy1 (20% identical), zebrafish zfx (20% identical), mouse Zfy1 (20% identical), mouse Zfy2 (19% identical). Paralogues in human: ZNF304 (59% identical), ZNF772 (56% identical), ZNF256 (51% identical), ZNF551 (48% identical), ZNF587B (48% identical), ZNF792 (47% identical), ZNF548 (46% identical), ZNF418 (46% identical), ZNF549 (44% identical), ZNF154 (41% identical), ZIK1 (40% identical), ZSCAN2 (38% identical), and 26 more.
Diseases named in the same sentence as ZNF134 in open-access papers:
ZNF134 is named in the same sentence as 2 diseases in open-access papers, as found by Europe PMC text mining. Sharing a sentence is not in itself a finding about the gene and the disease.
ZNF134 shares sentences with these, for which no sentence is quoted: osteoarthritis (1 paper); Parkinson disease (1).